SOX2 (SRY-box transcription factor 2)
Diseases named in the same sentence as SOX2 in open-access papers (continued):
Sharing a sentence is not in itself a finding about the gene and the disease.
bladder cancer (continued). "SOX2 has been shown to be upregulated and functionally relevant to various cancer, including bladder cancer." (PMID 36293387, 2022). "Previous reports have shown that SOX2 is a biomarker for cancer stem cells in human bladder cancer (BC), and our most recent study has indicated that the inhibition of SOX2 by anticancer compound ChlA-F attenuates human BC cell invasion." (PMID 36293387, 2022). "In conclusion, our results cast doubt on the reliability of ALDH1 and SOX2 as clinically relevant prognostic biomarkers in bladder cancer." (PMID 34211078, 2021). "Linsitinib, an IGF1R inhibitor, was used to block IGF2/IGF1R signaling-mediated AKT phosphorylation in SOX2-expressing bladder cancer cells." (PMID 32427884, 2020). "Although signaling elicited by the stem cell factors SOX2, OCT4, KLF4, and MYC has been associated with cancer progression in several tumors, it has remained unclear how these signaling molecules mediate bladder cancer progression." (PMID 32427884, 2020). "In this study, we found SOX2 is a prognostic marker in bladder cancer patients, signifying poor survival." (PMID 32427884, 2020). "Our study revealed that SOX2OT functions as a miRNA sponge to positively regulate the expression of SOX2 by sponging miR-200c and subsequently promoting the stemness phenotype of BCSCs, thus playing an oncogenic role in bladder cancer pathogenesis." (PMID 32019566, 2020). "This suggests that IGF2 and IGF1R are crucial for SOX2-mediated growth and survival of bladder cancer cells." (PMID 32427884, 2020). "Because 5637 represents a bladder cancer cell line with high SOX2 expression, we adopted the lentiviral shRNA system to knock down SOX2 in 5637 cells to further investigate the effect of eliminating SOX2 function." (PMID 32427884, 2020). "Lastly, pharmacological inhibition of IGF1R, using linsitinib, also inhibited the SOX2-mediated spheroid formation of bladder cancer cells under low-serum stress." (PMID 32427884, 2020). "ChIP-qPCR analysis showed that the signal of H3K4me3, a predominant mark of active promoters, increased upon SOX2 expression in bladder cancer cells." (PMID 32427884, 2020). "In this study, we found SOX2 expression signifies poor recurrence-free survival and correlates with advanced pathological grade in bladder cancer." (PMID 32427884, 2020). "The limitation of this study is that we mainly used T24 and 5637 cells, which represent muscle invasive bladder cancer cell lines maintained in different media, to dissect the potential oncogenic role of SOX2 in bladder cancer." (PMID 32427884, 2020). "SOX2OT functions as a miRNA sponge to positively regulate SOX2 expression by sponging miR-200c and subsequently promotes the stemness phenotype of BCSCs, thus playing an oncogenic role in bladder cancer pathogenesis." (PMID 32019566, 2020). "Here, we observed that only SOX2 expression correlates with poor recurrence-free survival of bladder cancer patients." (PMID 32427884, 2020). "On the one hand, tumors harboring ESC-like gene expression signature with active targets of SOX2, OCT4, and MYC were associated with poor pathological differentiation and poor prognosis in brain, breast, and bladder cancer patients." (PMID 32427884, 2020). "SOX2 silencing attenuated bladder cancer cell growth, while its expression promoted cancer cell survival and proliferation." (PMID 32427884, 2020). "Assessing SOX2 expression in bladder cancer cell lines showed its expression was considerably lower in T24 cells than in 5637 cells." (PMID 32427884, 2020). "Our findings provide insights on SOX2-mediated oncogenesis in bladder cancer and highlight putative therapeutic targets." (PMID 32427884, 2020). "All these data verify SOX2 promotes bladder cancer cell growth and survival by inducing IGF2/IGF1R signaling." (PMID 32427884, 2020). "We observed that pharmacological inhibition of AKT phosphorylation attenuates bladder cancer cells’ SOX2-mediated survival and spheroid-forming capability." (PMID 32427884, 2020).
bladder cancer (continued). "Recent study found that LBCS inhibits self-renewal, chemoresistance and tumor initiation of bladder cancer stem cells by guiding the hnRNPK-EZH2 complex to repress the expression of SOX2." (PMID 31221168, 2019). "Our previous study reportes that LBCS binds and recruits hnRNPK-EZH2 complex to inhibit the expression of SOX2 in the nuclei of bladder cancer stem cells." (PMID 31221168, 2019). "Until now, no study has assessed the relationship between the expressions of SOX2 and livin in bladder cancer." (PMID 28983346, 2015). "Overall, the correlation observed between SOX2 and livin expression in primary urinary bladder carcinomas was significantly positive (P < 0.001)." (PMID 28983346, 2015). "Accordingly, the results on the role of SOX2 in bladder cancer were coincided with that in other cancers." (PMID 28983346, 2015). "Similarly, studies have shown that Sox2 regulates autophagy pathways in colorectal and bladder cancers, promoting chemotherapy resistance and cancer stem cell traits." (PMID 39875055, 2025). "Thus, it seems that an increased expression of SOX2 promotes the development of an aggressive form of bladder cancer with more mesenchymal features." (PMID 37298099, 2023). "The qRT-PCR analysis demonstrated that the loss of TrkB significantly decreases the accumulation of the CSC population by induction of CSC markers expression, including Nanog and SOX2, which are positively correlated with tumor grade and stage in bladder cancer." (PMID 37749450, 2023). "HuR also enhances the stability and promotes the translation of ubiquitin-specific protease 8 by binding to its mRNA, which subsequently promotes the ubiquitination and degradation of SOX2 by acting as an E3 ligase, thereby inhibiting the invasive ability of bladder cancer." (PMID 36831493, 2023). "In addition, isorhapontigenin inhibits human bladder cancer invasion via an upstream regulatory Dicer/miR-145/SOX2/miR-365a/RAC1 cascade resulting in MKK7/JNK activation and autophagy induction." (PMID 36766800, 2023). "With its higher expression in bladder cancer, SOX2 may be a potential target for bladder cancer therapy." (PMID 37298099, 2023). "Summary of non-coding RNAs regulating SOX2 expression in bladder cancer." (PMID 36465380, 2022). "Finally, the expression of β-catenin and some of the CSC markers analyzed in our study, such as ALDH1A1, Sox-2 or Oct-4, correlates with tumor grade, recurrence, metastasis or worse survival in patients with bladder cancer." (PMID 35008872, 2021). "Moreover, qRT-PCR and WB showed that the expression levels of stemness-associated biomarkers, such as OCT4, ABCG2 and SOX2 were markedly elevated in ATF5-overexpressed SW780 and UM-UC-3 cells, whereas reduced in ATF5-silenced bladder cancer cells." (PMID 34895217, 2021). "By contrast, long-term culturing of T24 spheroids under low-serum condition (1% FBS) attenuated the size of the spheroids; however, SOX2 expression sustained the T24 spheroid-forming capability under the low-serum condition, indicating SOX2 is involved in bladder cancer cell survival." (PMID 32427884, 2020). "Moreover, we found that SOX2 promotes bladder cancer cell survival by inducing the IGF2/IGF1R pathway, thereby activating AKT survival signaling." (PMID 32427884, 2020). "Hence, our findings that SOX2 activates IGF2/IGF1R signaling and predicts poor prognosis further link IGF2/IGF1R signaling to SOX2 mediated aggressiveness in bladder cancer." (PMID 32427884, 2020). "Furthermore, pharmacological inhibition of AKT phosphorylation, using MK2206, inhibited the SOX2-mediated spheroid formation of bladder cancer cells." (PMID 32427884, 2020). "Furthermore, we identified IGF2 and IGF1R as AKT upstream molecules which induce AKT phosphorylation in SOX2-positive bladder cancer cells." (PMID 32427884, 2020). "To further verify whether AKT activation mediates SOX2-induced bladder cancer survival, we pharmacologically inhibited AKT activation with MK2206." (PMID 32427884, 2020).
bladder cancer (continued). "Our present results confirmed that SOX2 regulates IGF2/IGF1R signaling in bladder cancer cells." (PMID 32427884, 2020). "Indeed, we found that pharmacological inhibition of IGF2/IGF1R signaling with linsitinib decreased AKT phosphorylation and attenuated bladder cancer cells’ SOX2-mediated colony-forming ability." (PMID 32427884, 2020). "Accumulating evidence has indicated that SOX2OT plays a key role in the transcriptional regulation of the SOX2 gene and that SOX2 is a marker for stem-like tumour cells in bladder cancer, suggesting that SOX2OT may play an important regulatory role in BCSCs." (PMID 32019566, 2020). "To understand whether IGF2/IGF1R signaling is responsible for high-SOX2 expressing bladder cancer cell growth, we knocked down IGF2 and IGF1R." (PMID 32427884, 2020). "This suggests SOX2 expression promotes bladder cancer cell growth." (PMID 32427884, 2020). "SOX2 expression had been shown as a potential CSC marker in bladder cancers (BCa) where SOX2-expressing cells could seed the BCa, and lineage-specific ablation of SOX2-expressing cells enhanced tumor regression." (PMID 30517668, 2020). "Moreover, Higher SOX2 expression is related to bladder cancer patients’ shorter overall survival (OS) and disease-free survival (DFS) in TCGA-BLCA." (PMID 32019566, 2020). "Interestingly, lncRNA-LBCS directly binds to the hnRNPK–EZH2 complex and guides it to the SOX2 promoter and induces H3K27me3 to inhibit SOX2 expression, contributing to the attenuation of bladder cancer initiation and chemoresistance." (PMID 30658384, 2019). "Recent studies have shown that Sox2, a putative undifferentiated marker, may be involved in the behavior of CSCs in skin squamous cell carcinoma and bladder cancer cells." (PMID 30518951, 2018). "Recent studies have shown that Sox2 may also be involved in the maintenance of cancer stem cells (CSCs) in skin and bladder cancers." (PMID 30518951, 2018). "Consistent with previous gene expression results, SOX2, the key gene regulator of pluripotency, was detectable in about 30% of the urothelial carcinoma, thus emphasizing the presence of different stem-like and differentiated cell populations within the bladder carcinoma." (PMID 26452033, 2015). "SOX2 and livin may contribute to the progression of bladder carcinoma." (PMID 28983346, 2015). "For example, the expression of stem cell markers such as SOX2, IGF1R, SOX4, ALDH1, and CD44 affects the likelihood of recurrence and metastasis in bladder cancer." (PMID 41153362, 2025). "Among these 9 potential targets, SOX2-clinically correlated with poor prognosis and aggressive BCa subtypes -emerged as a key potential mediator of YTHDC2’s function in bladder cancer." (PMID 41145440, 2025). "lnc-LBCS repress the SRY-box 2 (SOX2) transcription, which is essential factor in the self-renewal of bladder cancer stem cell populations." (PMID 40149464, 2025). "In bladder cancer, lncRNA SOX2OT acts as a ceRNA of miR-200c and promotes EMT, invasion, and bladder cancer stem cell activity through increased SOX2 expression." (PMID 39937018, 2025). "Cytokeratin 14 (KRT-14), aldehyde dehydrogenase 1a (ALDH1a), and the transcription factors SOX2 and CD44 have been shown to initiate bladder cancer." (PMID 38607066, 2024). "PTPN12 depletion (shPTPN12) in the weakly metastatic breast and bladder cancer lines (UMUC3) increased ES-TF expression whereas PTPN12 transduction in 1833 decreased NANOG, MYC, and SOX2 expression." (PMID 38886396, 2024). "Our results reveal that the expression levels of stemness (SOX2, c-MYC, Nanog, and OCT4) and EMT (N-cadherin) markers are positively correlated with the cisplatin resistance development of bladder cancer cells." (PMID 38139437, 2023). "METTL3 enhances the AFF4 RNA’s m6A modification and expression in bladder cancer stem cells (BCSCs), which directly controls the expression of MYC and SRY-Box Transcription Factor 2 (SOX2) in BC cells to enhance tumourigenesis in BC." (PMID 37284313, 2023).
bladder cancer (continued). "In another study, Migata et.al show a relationship between epithelial-mesenchymal transition (EMT) and cancer stemness and a decrease in E-cadherin increased the expression of SOX2 and NANOG in bladder cancer cell lines." (PMID 37298099, 2023). "It has been reported that SOX2OT inhibition can restrict the bladder cancer stem cell (CD44+, ALDH1+) self-renewal and cisplatin resistance by SOX2 regulation." (PMID 36548179, 2022). "The tumor suppressor lncRNA LBCS is downregulated in bladder cancers, which otherwise recruits hnRNPK and EZH2 to the promoter of SOX2 gene to induce H3K27me3 repressive tri-methylation, thus suppressing SOX2 expression." (PMID 36010595, 2022). "EMT promoted stemness involving the overexpression of SOX2 and NANOG in muscle-invasive bladder cancer clinical samples." (PMID 33911182, 2021). "At present, great progress has been made in the research of molecular markers on bladder cancer stem cells surface, such as CD133, Nanog, Oct4, Sox2, and ALDH1." (PMID 34026626, 2021). "To further examine the potential of SOX2, SOX4, and IGF1R signaling in bladder cancer prognosis, we correlated the expression of these molecules with recurrence-free survival in primary bladder tumors." (PMID 32427884, 2020). "In conclusion, we demonstrated that SOX2 stimulated IGF2 expression to activate AKT signaling, enhancing the survival and spheroid-forming capability of bladder cancer cells." (PMID 32427884, 2020). "Mechanistically, we found that SOX2OT expression positively correlated with SOX2 expression in bladder cancer, and SOX2OT knockdown inhibited SOX2 expression in BCSCs." (PMID 32019566, 2020). "Under low-serum stress, SOX2 expression promoted AKT phosphorylation and bladder cancer cells’ spheroid-forming capability." (PMID 32427884, 2020). "We discovered that, under low-serum stress, SOX2 expression induces AKT phosphorylation and sustains bladder cancer cells’ spheroid-forming capability." (PMID 32427884, 2020). "Therefore, the lncRNA–LBCS/hnRNPK–EZH2/SOX2 regulatory axis acts as a tumor suppressor in bladder tumorigenesis and progression, and could be considered as a therapeutic target for clinical intervention in chemoresistant bladder cancer." (PMID 30658384, 2019). "We found no significant line of demarcation between bilharziasis associated and non-bilharziasis associated bladder carcinomas regarding their SOX2 and livin expressions suggesting that bilharziasis may have no significant role in up-regulation of either SOX2 or livin in TCC and SCC." (PMID 28983346, 2015). "Then, the expression of previously identified bladder cancer stem cell markers (POU5F1, BMI1, NANOG, SOX2,) was determined by real- time qPCR in the established control NT and αv kd cell lines as well as in GLPG0187 treated cells." (PMID 25247809, 2014). "In the context of lung adenocarcinoma, CAMK2A has been demonstrated to support tumor-initiating cells by upregulating SOX2 through the phosphorylation of EZH2, indicating a potential mechanism by which it may also affect bladder cancer." (PMID 40893939, 2025). "In our research, we found that forced decreased expression of KCNMB2-AS1 would inhibit the expression of CD133, Nanog, Oct4, Sox2, ALDH1 and prevent the ability of stemness of bladder cancer cell lines, which would provide a new target of Bladder cancer treatment." (PMID 34026626, 2021). "The molecular mechanism linking SOX2 expression to poor prognosis in bladder cancer has not been well understood." (PMID 32427884, 2020). "Because factors in ESC signaling and iPSC reprogramming have been linked to tumor malignancy, we used the Cox’s proportional hazards model to analyze the link between SOX2, KLF4, MYC and OCT4 expression and recurrence-free survival outcome for bladder cancer patients." (PMID 32427884, 2020). "Moreover, we observed SOX2 and IGF1R levels are significantly correlated with poor prognosis in bladder cancer patients." (PMID 32427884, 2020).
bladder cancer (continued). "SOX2OT and SOX2 expression levels were significantly upregulated in BCSCs compared with bladder cancer non-stem cells (BCNSCs)." (PMID 32019566, 2020). "SOX2 is a known marker of stemness not expressed in healthy urothelial cells and related to the presence of cancer stem cells (CSCs), also in bladder cancer." (PMID 33322565, 2020). "METTL3 may maintain the characteristics of bladder cancer stem cells by inducing the m6A modification of SOX2(SRY-Box Transcription Factor 2), a marker of bladder cancer stem cells both in vivo and in vitro." (PMID 32765970, 2020). "For instance, lnc-LBCS could dramatically attenuate bladder cancer initiation and chemo-resistance via guiding hnRNPK-EZH2 complex to the SOX2 promoter and mediating histone H3 lysine 27 trimethylation (H3K27me3)." (PMID 31335317, 2019). "Lnc-LBCS was shown to inhibit the self-renewal and chemoresistance of bladder cancer stem cells through the epigenetic silencing of SOX2, which was partly through H3K27me3 deposition facilitated by binding the EZH2 component of PRC2 and hnRNPK to the SOX2 promoter via triplex-DNA formation." (PMID 37444543, 2023). "Since our evidence suggests that SOX2 activates AKT survival signaling and promotes spheroid-forming ability by inducing IGF2/IGF1R in bladder cancer cells, IGF2 and IGF1R may be potential therapeutic targets for treating bladder cancer." (PMID 32427884, 2020). "SOX2 was expressed in pre-neoplastic and invasive bladder tumors, whereas it was absent in normal urothelial cells and SOX2 could facilitate tumor invasiveness through generation of stem cells in bladder cancer." (PMID 30517668, 2020). "Since SOX2 mediates stem cell differentiation and iPSC reprogramming mainly via epigenetic regulation, whereby H3K4me3 marks sites with active gene expression, we examined whether H3K4me3 signal on the IGF2 locus is affected by SOX2 expression in bladder cancer cells." (PMID 32427884, 2020). "We found that SOX2, but not OCT4, KLF4, or MYC expression, correlates with poor prognosis and histologic differentiation in bladder cancer." (PMID 32427884, 2020). "Kaplan-Meier analysis showed that SOX2, but not SOX4, expression correlated with a poor recurrence-free survival in bladder cancer patients, and the patients harboring a SOX2-high/SOX4-low signature had a worse recurrence-free survival outcome than those with SOX2-low/SOX4-high signature." (PMID 32427884, 2020). "POU5F1 has also been shown to have an important role in bladder cancer stem cells, invasion and migration, however, our data suggest that αv integrin might affect migration through a mechanism independent of POU5F1, for example via NANOG or SOX2." (PMID 25247809, 2014).